ENSG00000258052 (novel protein)
Gene: Protein-coding gene on chromosome 12 (69,801,669 to 69,855,363, forward strand). Ensembl gene ENSG00000258052.
Genetic constraint (gnomAD): Missense variants: 27 observed, 28.04 expected, observed/expected ratio (o/e) 0.96, 90% interval 0.71 to 1.33. Synonymous variants: 12 observed, 10.67 expected, observed/expected ratio (o/e) 1.12, 90% interval 0.72 to 1.75.